RN7SL748P (RNA, 7SL, cytoplasmic 748, pseudogene)
Gene: Miscellaneous RNA gene on chromosome 6 (36,522,191 to 36,522,501, forward strand). Ensembl gene ENSG00000239964.
Homologues: Orthologues: chimpanzee Metazoa_SRP (99% identical), macaque Metazoa_SRP (90% identical). Paralogues in human: RN7SL2 (80% identical), RN7SL1 (80% identical), RN7SL3 (79% identical), RN7SL7P (79% identical), RN7SL220P (78% identical), RN7SL712P (78% identical), RN7SL448P (77% identical), RN7SL597P (77% identical), RN7SL408P (77% identical), RN7SL804P (77% identical), RN7SL732P (77% identical), RN7SL769P (77% identical), and 705 more.